NQO1 (NAD(P)H quinone dehydrogenase 1)
Diseases named in the same sentence as NQO1 in open-access papers (continued):
Sharing a sentence is not in itself a finding about the gene and the disease.
tumor (continued). "Along with KEAP1 mutations, the expression levels of two Nrf2 downstream transcripts expressions, Ho-1 and Nqo1, were found significantly associated with tumor invasiveness and patients survival in NSCLC advanced stage." (PMID 27847554, 2016). "In EC, a significant association was noticed between increased NQO1 mean expression and tumor grade (P = 0.011)." (PMID 28983331, 2015). "The NQO1 609 TT genotype has been associated with an increased risk for various tumour types including gastrointestinal and urological cancers." (PMID 19822020, 2009). "Our hypothesis was that this selectivity would be explained by the high level of NQO1 in female genitourinary tumors, as this enzyme is strongly associated with the progression of these tumor types, as indicated by previous studies." (PMID 40573233, 2025). "Furthermore, NQO1 is implicated in cellular metabolism and signal transduction pathways, impacting tumor cell proliferation and PCD." (PMID 39600313, 2024). "Similarly, ARQ 761 is a β-lapachone analogue that exploits the unique elevation of NQO1 found in solid tumors to cause tumor-specific cell death." (PMID 37175546, 2023). "NQO1 was reported to be overexpressed in breast cancer, lung cancer, colon cancer, and pancreatic cancer, which were closely associated with tumor occurrence and development." (PMID 37188198, 2023). "High NQO1 expression is associated with tumor metastasis, angiogenesis, and poor prognosis." (PMID 37695786, 2023). "Additionally, we discovered that NQO1 depletion renders cisplatin-refractory tumor spheroids highly susceptible to drug treatment." (PMID 36980879, 2023). "It is suggested that NQO1 expression may affect the level of tumor mutation burden and microsatellite instability in these tumors, and patients with tumors with high NQO1 expression may be more sensitive to immunotherapy." (PMID 37583897, 2023). "NQO1 encodes an enzyme with antioxidant properties and responds to oxidative stress in tumor cells." (PMID 36319669, 2022). "Indeed, mice knockout for the Nrf2 downstream target, Nqo1, displayed susceptibility to benzo(a)pyrene-induced tumor skin development." (PMID 33053665, 2020). "Together, our results indicate that low NQO1 is associated with advanced tumor stages and high levels of NQO1 may protect from tumor progression." (PMID 31909204, 2020). "The use of NQO1-bioactivatable drugs, therefore, may be a clinically viable approach to reduce the toxicity of IR associated with high doses and also to improve the tumor selectivity of treatment." (PMID 32974194, 2020). "ß-lapachone (ß-lap) could cause tumor-selective ROS formation in an NADPH:quinone oxidoreductase 1 (NQO1)-specific manner." (PMID 33117704, 2020). "Therefore, it can be suggested that the regulation of AKT and MAPK signaling pathways by NQO1 is one putative mechanism underlying tumor suppressive function of NQO1." (PMID 31886179, 2019). "Consistent with preclinical models, this effect may be associated with tumours that have high NQO1 expression, but further biomarker development and PK profiling will be required to identify optimal populations for this treatment strategy." (PMID 30318513, 2018). "ARQ 761 has modest single-agent activity, which appears associated with tumour NQO1 expression." (PMID 30318513, 2018). "Furthermore, the over-expression of NQO1 mRNA species predicted tumor recurrence in high-risk ER(+) that were LN(+) and had received endocrine-therapy (mostly tamoxifen), but not chemotherapy." (PMID 28411284, 2017). "Hypoxia and high oxidative stress are among the hallmark features of the tumour microenvironment, yet the molecular effects of NQO1 on cell survival and bioreductive anticancer drugs within the hypoxic tumour microenvironment are largely unknown." (PMID 27966538, 2016). "NQO1-null mice exhibited increased susceptibility to chemical-induced skin carcinogenesis." (PMID 27966538, 2016).
tumor (continued). "This was consistent with our hypothesis that lowered NAD+/NADH levels caused by FK866 would sensitize NQO1+ tumor cells to rapid futile redox cycling initiated by β-lap." (PMID 25590809, 2015). "This study was to determine whether the anti-tumor effect of tanshinone IIA (TSA) is NQO1 dependent and to elucidate the underlying apoptotic cell death pathways." (PMID 22848731, 2012). "Thus, NQO1:Catalase ratios in PDA tumor vs associated normal pancreas tissue potentially offer a significant therapeutic window that may be exploited using unique NQO1 bioactivatable drugs, such as ß-lap (ARQ761)." (PMID 26602448, 2015). "To overcome this, we developed a novel therapeutic strategy that simultaneously upregulates NQO1 expression and provides its quinone substrate within tumor cells." (PMID 42095505, 2026). "NAD(P)H:quinone oxidoreductase 1 (NQO1) is identified as a central regulator linking tumor-intrinsic survival to suppression of macrophage-T cell crosstalk." (PMID 41945867, 2026). "Pharmacologic inhibition of NQO1 using skullcapflavone II restores apoptotic sensitivity and enhances cisplatin efficacy, resulting in significant tumor suppression with favorable tolerability in preclinical models." (PMID 41945867, 2026). "β-Lap exerted anticancer effects through an effective redox cycle mediated by NAD(P)H: quinone redox reductase 1 (NQO1) and exhibited significant selectivity for NQO1-overexpressing tumor cells." (PMID 41355972, 2026). "In the mouse tumor model, the NQO1‐overexpressing group exhibited faster tumor growth and larger tumor volumes, with significantly elevated levels of CXCL12 in peripheral blood." (PMID 41028931, 2025). "The identified NQO1‐responsive DON prodrugs demonstrate highly promising anti‐tumor activities both in in vitro and in vivo models of resistance." (PMID 39680480, 2025). "We subsequently assessed the anti‐tumor efficacy of 10e in the NQO1‐hyperactivated HCC827OR transplantation tumor model." (PMID 39680480, 2025). "High NQO1 expression, localized to SNAI2+/CDH1low/CDH2high cells at the invasive front, facing the tumor stroma, is consistent with recent findings that NQO1 supports a sustained EMT response by stabilizing Snail transcriptional activity." (PMID 40600748, 2025). "A subcutaneous tumor model was established using HCCLM3 cells in nude mice to investigate the impact of NQO1 and SLC7A11 on tumor growth." (PMID 40007539, 2025). "Tumor growth monitoring indicated that relative to the control group, xenografts from the NQO1-silenced group showed significantly reduced tumor volume and weight (P < 0.01)." (PMID 39939940, 2025). "Immunohistochemical analysis revealed that NQO1 protein was expressed at a higher level in the tumor area of the KEAP1-KO tumor tissues than that of the WT tumor tissues." (PMID 41035689, 2025). "Plerixafor significantly suppressed tumor growth and improved therapy efficacy in NQO1‐overexpressing tumors." (PMID 41028931, 2025). "The combined inhibition of SLC7A11 and NQO1 had a more significant suppressive effect on tumor growth in the subcutaneous HCC model." (PMID 40007539, 2025). "To explore the impact of Plerixafor on the TME and tumor progression in vivo, we established mouse tumor models in the control, NQO1, and NQO1 combined with Plerixafor treatment group." (PMID 41028931, 2025). "Flow cytometry analysis and mIHC further confirmed that the infiltration of Treg cells in the tumor tissue was significantly increased in the NQO1‐overexpressing group, while the infiltration of Treg cells was significantly reduced in the sh‐NQO1 group." (PMID 41028931, 2025). "Real‐time PCR confirmed the overexpression of NQO1 mRNA in tumour tissue, which was further supported by elevated NQO1 protein levels compared to normal tissue." (PMID 39707614, 2025). "Immunohistochemical analysis showed that high NQO1 expression in the tumor area of the KEAP1-KO tumor tissues was reversed in that of the DKO tumor tissues." (PMID 41035689, 2025).
tumor (continued). "To validate the aberrant level of NOQ1, we evaluated NQO1 protein expression in the original tumour samples." (PMID 39707614, 2025). "In contrast, xenografts from the NQO1-overexpressing group exhibited considerable increases in both tumor volume and weight." (PMID 39939940, 2025). "In the system, the DNAzyme is designed to remain inactive and “caged” until an activating enzyme, such as the NAD(P)H quinone oxidoreductase (NQO1), which is overexpressed in tumor cells, is introduced." (PMID 40363763, 2025). "The lethality of β-Lap against tumor cells is NQO1-dependent, positively correlated with the levels of NQO1." (PMID 40585976, 2025). "Recent studies have shown that upregulation of Ho1 and Nqo1 synergistically promote tumor cell survival and inhibits apoptosis by regulating cellular glutathione levels." (PMID 39210798, 2025). "We established a mouse HCC model with NQO1 overexpression, and the results indicated that the NQO1 + aPD‐1 + lenvatinib + Plerixafor group exhibited significantly smaller tumor volumes, with stronger effects compared to other groups." (PMID 41028931, 2025). "By contrast, very low NQO1 expression was found in the tumor area of the DKO tumor tissues, indicating that NRF2 activation in the KEAP1-KO tumor is efficiently canceled in the DKO tumor tissues." (PMID 41035689, 2025). "Five of nine PDCs demonstrated high activity as well as high mRNA and protein levels of NQO1 that were comparable to the paired tumours." (PMID 39707614, 2025). "The results indicated that compared to the NQO1 group, the combined Plerixafor group exhibited significantly slower tumor growth and limited tumor volumes." (PMID 41028931, 2025). "While NQO1 is constitutively expressed at low levels in normal tissues, it is overexpressed in tumor tissues and particularly activated in Osimertinib‐resistant cells." (PMID 39680480, 2025). "NQO1 regulates the vitamin K cycle and promotes tumor progression via oxidative stress and metabolic reprogramming." (PMID 41028931, 2025). "NQO1 expression varies between neoplastic and normal cells and has garnered attention in tumor detection probe development owing to its distinct expression levels." (PMID 39939940, 2025). "In HCC cell lines and the subcutaneous xenograft model, the combined suppression of SLC7A11 and NQO1 significantly enhanced the inhibitory effect on tumor growth by inducing ferroptosis." (PMID 40007539, 2025). "The authors found mutations in four genes in the NRF2‐ARE pathway in 10% of pRCCs tested, and they also found that overexpression of the reductase NQO1 correlated with worse survival and higher tumor grade and stage." (PMID 39707614, 2025). "Higher magnification images clearly showed that high-level NQO1 expression was observed in tumor areas (shown by T) of the KEAP1-KO tumor tissues, because of the strong NRF2 activation." (PMID 41035689, 2025). "EMT has a crucial role in tumor invasiveness and metastasis; hence, we investigated the NQO1 influence on this process." (PMID 39939940, 2025). "IHC analysis showed NQO1 over‐expression in the five tumour tissues and PDCs (474, 193, 764, 177 and 1081) while we did not detect any significant difference in NRF2 staining." (PMID 39707614, 2025). "mRNA and protein expression analysis of NQO1 confirmed the activation of the NRF2‐ARE pathway in pRCC tumour tissues and in the paired PDCs." (PMID 39707614, 2025). "To enhance the safety and efficacy of DON, we synthesized a novel series of NQO1‐activatable prodrugs for targeting by leveraging the differential expression between tumor and normal tissues." (PMID 39680480, 2025). "Concurrently, MSCs were engineered with a hypoxia-inducible promoter and NAD(P)H: quinone oxidoreductase 1 (NQO1), responsible for regulating the production of IL-2 within the tumor microenvironment." (PMID 39971901, 2025). "35.3% of advanced stage tumours (pT3/4) but only 8.1% of low stage tumours (pT1/2) were NQO1‐positive (p = .0007)." (PMID 39707614, 2025).
tumor (continued). "Collectively, we observed a sex disproportional regulation of genes mechanistically linked to tumor growth, and we confirmed the cRaf-dependent regulations of CD177 and NQO1 in females LC patients." (PMID 38245882, 2024). "Elevated levels of NQO1 in tumor cells bolster the antioxidant capabilities of cells, thereby fostering tumor cell survival in adverse conditions." (PMID 39600313, 2024). "This probe was highly sensitive in detecting NQO1 both in lab tests and A549 tumor xenografts, with an emission at 695 nm." (PMID 39120303, 2024). "The team conducted in vivo imaging of A549 and LLC (a mouse lung cancer cell line) tumor model mice by detecting endogenous NQO1 levels." (PMID 39451714, 2024). "It has been shown that NQO1 is overexpressed in many human tumor tissues and its overexpression leads to resistance to chemotherapy in a variety of tumors." (PMID 39094401, 2024). "The tumor abundance of NQO1 has also been exploited to deliver anticancer drugs like SN-38, an active topoisomerase I (topo I) drug." (PMID 39120303, 2024). "Irrespective of these considerations, the overall higher expression justifies NQO1 as a unique and selective target for tumor imaging and therapy, as discussed in the sections to follow." (PMID 39120303, 2024). "The large Stokes shift of 149 nm was highly beneficial in distinguishing the tumor cells from their normal counterparts based on NQO1 content." (PMID 39120303, 2024). "NQO1 enzyme is often overexpressed in tumor cells and can catalyze the reduction of β-lapachone, generating plentiful ROS." (PMID 39500878, 2024). "Conversely, depletion of NQO1 significantly reduces cell proliferation, suggesting the critical role of NQO1 values in determining the proliferation of these tumor cells." (PMID 38167027, 2024). "There was good concordance between SLC7A11 (which encodes xCT), NQO1, GCLC and GCLM median expression levels across tumours, providing an ‘antioxidant signature’ associated with the NRF2 transcriptional programme." (PMID 39690148, 2024). "Understanding the role of NQO1 in the tumor immune microenvironment will help us better understand the mechanisms of tumor immune escape and provide guidance for the development of new immunotherapeutic strategies." (PMID 37583897, 2023). "Lastly, we investigated the effect that NQO1 depletion had on chemotherapeutic resistance using tumor spheroids." (PMID 36980879, 2023). "There was good concordance between SLC7A11 (which encodes xCT), NQO1, GCLC and GCLM median expression levels across tumours, providing an ‘antioxidant signature’ associated with the NRF2 transcriptional program." (PMID 38168428, 2023). "Bioinformatics analysis showed that the expression of NQO1 in HCC tumor tissues was higher than that in adjacent tissues and that this was an independent risk factor for poor prognosis of patients with HCC." (PMID 37695786, 2023). "We suggest that metrics other than NQO1:CAT should be considered when characterizing a HNSCC tumor and its capacity to respond to β-lapachone." (PMID 36978989, 2023). "To better understand the role of NQO1 in tumorigenesis and tumor maintenance, we investigated the relationship between NQO1 and the CSC phenotype." (PMID 36980879, 2023). "In 2020, Liu and coworkers reported the use of NAD(P)H:quinone oxidoreductase 1 (NQO1)-responsive photosensitizer-conjugated polymeric vesicles for tumor imaging and therapy." (PMID 37513233, 2023). "We have shown that NQO1 depletion in the general population of A549 and H292 NSCLC tumor cells is correlated with the loss of ALDHhigh activity." (PMID 36980879, 2023). "For example, studies have shown that targeting NQO1 can effectively trigger innate sensing within the tumor microenvironment, synergizing with immunotherapy to overcome adaptive drug resistance." (PMID 37583897, 2023).
tumor (continued). "NQO1 is an overexpressed enzyme in certain tumor types; it maintains homeostasis and impedes oxidative stress caused by elevated reactive oxygen species (ROS) in tumor cells." (PMID 36986837, 2023). "NQO1 is necessary for in vitro serial spheroid formation, resistance to cisplatin treatment, and in vitro limiting-dilution tumor formation." (PMID 36980879, 2023). "NQO1 levels were higher in the tumor group than in the normal group (p<0.001), with the median difference between the two groups being 2.261 (1.875–2.891)." (PMID 37695786, 2023). "We previously reported that Nrf2 and the Nrf2-regulated gene Nqo1 are downregulated in high-grade tumours that arise from Keap1/Nrf2 mutant models." (PMID 38168428, 2023). "We previously found that tumor NQO1 expression levels promoted many malignant characteristics, including tumorigenesis, anoikis resistance, and cellular invasion." (PMID 36980879, 2023). "In an HCC orthotopic transplantation tumor model, both NQO1 knockout and an NQO1 inhibitor blocked tumor growth and induced apoptosis, suggesting that NQO1 plays an important role in maintaining the proliferation of HCC cells." (PMID 37695786, 2023). "The approach mechanistically inhibited the proliferation of BC cells MDA-MB-231 in vitro, downregulated the expression of Nrf2 and its downstream genes HO-1 and NQO1, and promoted ROS production and accumulation in these tumor cells." (PMID 37175972, 2023). "In both shNQO1 knockdown models (A549 and H358), we found that NQO1 depletion reduced the ability of NSCLC cells to form primary tumor spheroids." (PMID 36980879, 2023). "We created a BR-RO model to predict NQO1 expression levels, which included both the whole-tumor and whole-peritumor regions." (PMID 37695786, 2023). "Subsequently, we assessed the NQO1 mRNA expression levels in 32 tumor cell lines extracted from the CCLE and 69 tumor cell lines extracted from the HPA databases." (PMID 37583897, 2023). "Together, these data strongly suggest a role for NQO1 in anchorage-independence and, thus, tumor cell growth and proliferation." (PMID 36980879, 2023). "In vivo tumor inhibition of NQO1-responsive polymeric vesicles was examined in A549 tumor-bearing mice." (PMID 35269324, 2022). "The Pharmacological prohibition of NQO1 and GCLC is a new therapeutic strategy for overcoming tamoxifen-resistance and also shows that the prediction of NQO1 as a biomarker has the significant prognostic value of tumor recurrence in BC patients." (PMID 35617355, 2022). "VK3 can catalyze ROS production through the specific overexpression of NAD(P)H:quinone oxidoreductase-1 (NQO1) in tumor cells and specifically improve the intracellular ROS level." (PMID 35464718, 2022). "High levels of NQO1 in tumor cells catalyze the released VK3 to produce ROS, resulting in the amplified release of PTX and reduced side effects." (PMID 35464718, 2022). "The tumor cells in the third row highlighted the heterogeneity of NQO1 abundance, demonstrating mixed FITC signal intensity values ranging between 1000 and 9000." (PMID 36359002, 2022). "NQO1 is highly expressed in tumor cells, and its silencing increases NF-κB levels and upregulates transcription associated with inflammation and tumorigenesis." (PMID 36699607, 2022). "NQO1 activity and protein expression level can be obtained through tumor biopsy, but NQO1 protein expression is affected by many factors." (PMID 36338728, 2022). "The anti-tumor effect of β-lap is related to the activation of NAD(P)H:quinone oxidoreductase (NQO1)." (PMID 35453310, 2022). "This study demonstrates that NQO1 protein expression is high in normal, tumor-adjacent tissue and that NQO1 expression varies depending on the cell type." (PMID 36359002, 2022). "The mRNA levels for NQO1 were increased in 25/48 tumours and decreased in the same two tumour samples, which also had lower pirin expression." (PMID 35204145, 2022).